IL6 (interleukin 6)
Diseases named in the same sentence as IL6 in open-access papers (continued):
Sharing a sentence is not in itself a finding about the gene and the disease.
influenza (continued). "While the high levels of IL-6 in severe influenza have been taken as an indication that IL-6 plays a role in exacerbating lung inflammation, recent work has demonstrated that IL-6 is, in fact, essential for reducing lung pathology during influenza infection." (PMID 33680987, 2021). "A study from our group showed that influenza-induced type I IFNs trigger the secretion of the pro-inflammatory cytokines IL-6 and IL-12 in dendritic cells." (PMID 33828999, 2021). "This is consistent with the fact that IL-6 plays a more obvious role in nervous system diseases related to influenza reported in the literature." (PMID 34246228, 2021). "Two such cytokines are IL-10 and IL-6, which have been shown to be powerful mediators of inflammation during influenza infection." (PMID 33680987, 2021). "It has been reported that people infected with influenza have higher levels of cytokines stimulated by type I IFNs (such as IL-6 and IFN-γ), and the chemokines IP-10 (also known as CXCL-10) and MCP-1 (CCL2)." (PMID 35154087, 2021). "The results showed that influenza infection induced significantly higher mRNA expressions of IL-1β, IL-6, TNF-α, IL-10, MCP-1, IP-10, IFN-γ, and IFN-β in lung compared with non-infection mice." (PMID 35154087, 2021). "Previous studies have shown influenza infection can cause the production of TNF-α, IL-1β, IFN-γ, and IL-6." (PMID 34552653, 2021). "Earlier studies also noted that patients with adenoviral respiratory infection had strong inflammatory responses and higher serum IL-6 levels than with influenza and RSV infection." (PMID 33622191, 2021). "The significant down-regulated of IL-6 concentration in leprosy cured patients suggested that influenza vaccination elicited inhibitory mechanism of inflammatory, break the balance of host's existing immune network." (PMID 34397815, 2021). "New data highlight the correlation between the excessive production of IL-6, as a major inflammatory mediator, and the hyperinflammatory state during influenza infection and subsequent increase in the illness severity." (PMID 34627297, 2021). "Although no studies have yet identified an immune suppressive role for MCs in resolving influenza infection, immune mediators such as IL-10 and IL-6 are known to play an important role in mitigating influenza pathology." (PMID 33680987, 2021). "Of note, GALNT3 levels were correlated with lower IL-6 response upon SARS-CoV-2 stimulation after influenza vaccination, possibly contributing to the beneficial effects of the vaccine." (PMID 34695164, 2021). "The role of MCs in mediating IL-6 expression during influenza infection, however, remains to be fully explored." (PMID 33680987, 2021). "A recent study exploring the effect of the influenza vaccination on reward learning in 41 young healthy subjects showed that increases in IL-6 in circulation predicted increased performance on the PRT." (PMID 34741019, 2021). "Administration of recombinant IL-6 rescues macrophages from influenza-induced apoptosis and increases MARCO expression which promotes phagocytosis of bacteria." (PMID 33828999, 2021). "This is likely to boost vaccine efficacy since vaccine-induced NK activation and cytokine production in response to influenza vaccination recruited IL-6-producing dendritic cells (DCs) to the lymph nodes, that supported anti-Influenza B cell responses." (PMID 32698362, 2020). "Some in vitro studies on influenza showed that selenium deficiency resulted in reduced antioxidant activity of cells and an important increase in the pro-inflammatory cytokine IL-6, altering the response to influenza of epithelial cells." (PMID 32984253, 2020). "Alongside increased viral loads, SP-A knockout mice infected with influenza develop epithelial injury and higher levels of IL-6, macrophage inflammatory protein 2 (MIP-2) and macrophage and neutrophil infiltration." (PMID 33542724, 2020).
influenza (continued). "Our findings in ANP32B+/+ and ANP32B−/− mice on the other hand suggest that ANP32B is required for the induction of a subset of pro-inflammatory cytokine responses (TNF-α, MCP-1, IL-1β, and IL-6), upon influenza infection in the murine lung." (PMID 32231671, 2020). "In sum, our results demonstrate that there is augmented IL-1β and IL-6 production in aged lung in response to a post-influenza infection with S. pneumoniae." (PMID 32545261, 2020). "Tumor necrosis factor-α (TNF-α) and interleukin-6 (IL-6) production by circulating monocytes were persistent, a complex pattern different from influenza or bacterial sepsis." (PMID 33747973, 2020). "Influenza also induces epithelial cell release of a variety of cytokines and chemokines, including TNFα, IL-8, IL-6, CCL2, CCL5, CXCL1, and CXCL10, which attract macrophages and neutrophils to the infection site." (PMID 33193350, 2020). "We therefore also examined the presence of influenza-specific IgG in the serum of WT and IL-6 KO infants 3 weeks post-immunization." (PMID 33193346, 2020). "The higher level of IgG3 production was found to be positively correlated with the level of tumor necrosis factor-α (TNF-α) and interleukin-6 (IL-6) because IL-6 is the major cytokine produced during influenza infection." (PMID 33302987, 2020). "Our results illustrate that, in response to a primary influenza infection, there was diminished bacterial clearance and heightened production of pro-inflammatory cytokines, such as IL6 and IL1β." (PMID 32545261, 2020). "As IL-6 production is controlled by changes in NFҡB signaling, we next investigated the impact of influenza on the expression of several components of the NFҡB pathway." (PMID 32545261, 2020). "IL-6 gene expression was increased in both Nano-11-containing influenza vaccine groups compared to other vaccinates." (PMID 32443416, 2020). "We have used a C57BL/6 mouse model of infection with a laboratory- adapted strain of influenza (PR8) to delineate the importance of the cytokine IL-6 in the innate response to primary infection and in the development of protective immunity in adult mice." (PMID 33193346, 2020). "We next investigated the contribution of IL-6 to the protective effect of i.n. immunization with inactive influenza." (PMID 33193346, 2020). "There was a significant increase in IL-1β and IL-6 mRNA as well as IL-1β and IL-6 cytokine production in aged lung in response to secondary post-influenza infection with S. pneumoniae." (PMID 32545261, 2020). "Both serum CRP level (117.6 ± 88.1 vs. 78.5 ± 75.2, P = 0.017) and IL-6 level (133.5 ± 149.2 vs. 69.9 ± 100.0, P = 0.021) of severe influenza patients with aspergillosis were greatly higher than those without aspergillosis." (PMID 33537328, 2020). "Depletion of either IFNγ or IL-6 resulted in reduced frequency of influenza-specific antibody secreting cells." (PMID 32698362, 2020). "Previously, IL-6 has been established as an essential biological mediator in the relationship between psychological stress and illness expression following both influenza and rhinovirus infections." (PMID 32140685, 2020). "Increased IFN-γ signaling exacerbates bacterial pneumonia post-influenza infection; however, IL-6 has inhibition effects on IFN-γ." (PMID 32038632, 2019). "Influenza infection induces a variety of inflammatory cytokines and chemokines such as IL-6, IL-8, TNFα, CCL2, CCL5, CXCL10, and recruitment of neutrophils and macrophages to clear the virus." (PMID 31159430, 2019). "Using both human volunteers and mouse models (adults vs. aged) they find that adult females have more robust interleukin-6 production and greater titers and quality of influenza-specific antibodies." (PMID 31312529, 2019). "In influenza-infected macrophages from IL-6−/− animals, the phagocytosis of S. pneumoniae was weakened." (PMID 32038632, 2019).
influenza (continued). "The progression and resolution of symptoms from influenza infection can be related to the viral load and the elevation of inflammatory cytokines such as IL-6 and IP-10." (PMID 31013822, 2019). "IL-6 reduced cells death in BALF from influenza-triggered death maintaining homeostasis, leading to decreased susceptibility to secondary infection." (PMID 32038632, 2019). "A pro-inflammatory immune response to influenza and pneumococci is accompanied by the induction of IL-1, IL-6, TNF-, RANTES, MIP-1-alpha, IL-8, IL-10 and gamma interferon." (PMID 31513620, 2019). "In conclusion, these findings demonstrate that IL-6 from the lungs induced by influenza infection exerts a protective effect on the host preventing secondary pneumococcal infections in the post-influenza period." (PMID 32038632, 2019). "We found that ponatinib can also reduce MCP-1, KC (functional analogs of human IL-8), IP-10, and IL-6 productions dose-dependently in PCLS infected with influenza." (PMID 31293574, 2019). "In order to test in silico predictions and exploit the observed therapeutic potential of cytokine-specific neutralizations, antibody-mediated neutralizations of IFN-γ and/or IL-6 were performed in vivo post primary influenza infection." (PMID 31474978, 2019). "The role of DUSP10 in respiratory viral infection has also been examined in vivo: DUSP10 knock out mice infected with influenza had elevated levels of IL-6 in bronchoalveolar lavage (BAL) than wild-type mice." (PMID 30764493, 2019). "The co-infected mice were treated with a neutralizing IL-6-specific antibody administered to the respiratory tract together with the secondary pneumococcal infection on day 7 post influenza infection." (PMID 31474978, 2019). "In lung homogenates, influenza by itself caused mildly elevated levels of TNF-α, IL-1β, IL-6, and IL-10 at 4 days post-infection and to a lesser extent at 10 days after infection." (PMID 29978355, 2018). "Influenza infection also induces the production of such cytokines as TNFa, IL-1, IL-6, and the mononuclear cell attractant chemokines: CCL-3, CCL-4, CCL-5, CXCL9, CXCL10, and CXCL11 in human monocytes, epithelial cells, and rat alveolar or murine macrophages." (PMID 30037133, 2018). "Influenza infection induced a variety of inflammatory cytokines such as IL-1β, IL-6, TNFα, IL-8, CCL2, CCL5, and CXCL10 from epithelial and immune cells." (PMID 30337919, 2018). "Maternal immune activation (e.g., via an infectious exposure such as influenza) has been reported to be associated with risk of SZ and autism, and blood levels of cytokines (e.g., IL1B, IL2RA, IL-6, and TNF) are elevated in SZ patients (see reviews)." (PMID 30115913, 2018). "Support for our findings is also evident in the recent reports that demonstrate that influenza HA or modified versions thereof can inhibit IL-17A and IL-6 production in mice with subsequent beneficial effects on collagen-induced arthritis." (PMID 30192848, 2018). "We found an increase in the levels of the inflammatory cytokines IL-1α, IL-1β, TNFα, IL-6, IL-12p40, IL-17, and IFNγ, and increased levels of the Type 2 cytokines IL-4 and IL-5, in influenza-infected Stat2−/− mice when compared to WT mice." (PMID 30337919, 2018). "We show that IL-6 not only acts as an immune regulator to defend against influenza, but also plays an important role in balancing lung environment." (PMID 28262742, 2017). "Instead, in accordance with data derived from influenza infection models, IL-6 was required for the development of virus-specific T cell responses in MCMV." (PMID 28240600, 2017). "In response to influenza A virus-infection, macrophages produce large amount of cytokines such as IL-6, TNF-α, and MCP-1." (PMID 28352642, 2017). "We also compared interleukin-6 (IL-6) levels in the lungs of the control and vaccinated monkeys, because IL-6 levels are known to correlate with influenza severity." (PMID 28931922, 2017).
influenza (continued). "It is still obscure how IL-6 controls influenza-induced pneumonia, the subsequent lung fibrosis and regeneration of epithelial cells from severe injury after influenza infection." (PMID 28262742, 2017). "Our results showed that indirubin treatment lessened the production of TNF-α, IL-1β and IL-6 while enhanced the production of IL-10 in the lung tissues of influenza-infected mice loaded with stress." (PMID 29285277, 2017). "Collectively, these results implicate a protective role for IL-6 in influenza infection by reducing fibroblast accumulation and enhancing ECM turnover in the lung." (PMID 28262742, 2017). "The adenovirus-vectored influenza vaccine, rAdH5/M2e, stimulated modest levels of IL-6 as compared to immunization with FiPR8+CT or live PR8." (PMID 28825679, 2017). "On the other hand, vaccination resulted in greater IL-6 responses that are important for the resolution of influenza-mediated inflammation and the coordination of optimal T cell responses to influenza infection." (PMID 29267331, 2017). "Upon entry into respiratory epithelial cells (upper and lower respiratory tract and alveolar cells), influenza triggers production of several pro-inflammatory cytokines and chemokines such as interferons, IL-1β, IL-8, IL-6 and TNF-α19." (PMID 28106111, 2017). "We identify a novel role for IL-6 produced by fibroblasts during influenza infection in promoting apoptosis and reducing proliferation of fibroblasts, as well as balancing fibroblast migration through downregulating TGF-β production." (PMID 28262742, 2017). "After challenge with influenza A/Puerto Rico, IL-6 levels in asthmatic mice slowly increased to 161.7 pg/mL by 3 days post-infection, and then reached 654.7 pg/mL at 7 days post-infection." (PMID 28831046, 2017). "Elevation of IL6 has been observed in influenza-infected humans, primates, and ferrets, which appear to correlate with symptom severity." (PMID 29184367, 2017). "In particular, the TG/GG allele of rs8099917 shows significantly lower levels of IFN-α, IL2, and IL6 secretion in influenza-stimulated PBMCs." (PMID 28293236, 2017). "CXCL10 and IL6 are known to be highly elevated after influenza infection, and the previous cytokine-chemokine analysis indicated that plasma CXCL10 was correlated with viral loads." (PMID 27088501, 2016). "This idea is consistent with a report which demonstrated that pretreatment of influenza-infected mice with 1-MT, increased inflammatory markers, such as IL-6, TNF-α and IFN-β, and Th1 cell numbers and boosted the secondary immune response." (PMID 27695127, 2016). "We observed that PBMCs from older adults produce lower IL-2 levels and higher IL-6 levels following an influenza challenge when compared to those from younger individuals." (PMID 27322555, 2016). "Increases in IL-6 and IFNγ have also been observed in nasopharyngeal lavage samples taken from influenza patients, BAL samples taken from flu infected rhesus macaques and BAL samples from rhesus macaques infected with pulmonary nontuberculous mycobacteria." (PMID 27677639, 2016). "The time-dependent production of two key inflammatory cytokines, interferon (IFN-γ), and interleukin 6 (IL-6), which have been shown to be increased during severe influenza infection was confirmed by ELISA." (PMID 27536272, 2016). "Results compiled from young and older subjects also show this effect of IL-2 plus IL-6 on influenza-specific cells after 5 days of culture." (PMID 27322555, 2016). "Several studies have examined correlation of flu disease parameters such as viral shedding and symptom scores with levels of IL-6, which was recently reported as a potential biomarker of severity in pandemic influenza infections." (PMID 27110056, 2016). "Here we report that addition of exogenous IL-2 and IL-6 to influenza challenged PBMC, enhances the expansion and survival of the aged CD8+ T cell recall response, leading to more effector CD8+ T cells with higher cytotoxic activity." (PMID 27322555, 2016).
influenza (continued). "In HLA-A2+ donors, MHC Class I tetramer staining showed that adding both exogenous IL-2 and IL-6 resulted in greater differentiation into influenza-specific effector CD8+ T cells." (PMID 27322555, 2016). "In conclusion, our findings indicate that IL-6 secreted by AMs in response to epithelial TGF-β prevents development of ALI in influenza-infected HETs." (PMID 25840995, 2015). "The average concentration of IL-6 secretion from LPS-stimulated PBMCs of participants without self-reported cold or flu episodes was 12.17 ± 1.34 ng/ml and the concentration of IL-6 secretion from participants with cold or flu episodes was 17.00 ± 1.64 ng/ml." (PMID 25788896, 2015). "For inactivated influenza and x31/Ova cohorts, modest cytokine induction was observed characterized by IL-6 and tumor necrosis factor alpha (TNF-α) transcript upregulation." (PMID 26161083, 2015). "Our study reveals that IL-6 was significantly elevated (>10-fold above controls) in both pandemic waves, suggesting a better infection control because high concentrations of IL-6 have proven to confer protective effects against influenza." (PMID 26696552, 2015). "One case report described a systemic onset JIA (soJIA) patient on anti-IL6 who received two seasonal influenza vaccines and had a disease flare after both vaccinations." (PMID 26025339, 2015). "Neutralization of TGF-β and IL-6 alters bronchoalveolar lavage fluid chemokine and cytokine responses to influenza infection." (PMID 25840995, 2015). "Together, our data show that TGF-β-dependent production of IL-6 by AMs later in influenza infection prevents ALI development in HETs." (PMID 25840995, 2015). "By performing cytokine neutralization and bone marrow transfer experiments, we found that TGF-β produced early in response to influenza infection prevents ALI development in HET mice by inducing AM production of IL-6 later in infection." (PMID 25840995, 2015). "Levels of SPA also correlated with IL-6, which has been proposed as a marker for inflammatory damage in influenza." (PMID 24505273, 2014). "In area under curve analyses, post-LAIV IL-6 responses (P = 0.03) and influenza sequences (P = 0.01) were significantly reduced in NLF from BSH-treated smokers, whileNAD(P)H: quinoneoxidoreductasein NLF cells was significantly increased." (PMID 24910991, 2014). "The elevation of plasma IL-6 has been reported as the common feature in influenza patients including children, and therefore, the immune responses to poly I:C and influenza virus are similar despite differences in the signaling pathways." (PMID 25045603, 2014). "Taken all together, it appears that IL-6 is elevated in all types of influenza infection and IP-10 is another potentially important cytokine in influenza infection." (PMID 25003343, 2014). "Consistent with clinical reports, IL-6 was also increased during the host response to pH1N1 infection in mice, supporting the idea that IL-6 is an indicator of disease severity for influenza infection." (PMID 25003343, 2014). "SOCS1−/−IFN-γ−/− mice exhibited significantly decreased production of IL-6 and IL-10 at 7 dpi but increased IL-4, IL-5 and IL-13 levels in airways during influenza infection." (PMID 25500584, 2014). "Increased levels of Th1 and Th2 cytokines, such as interferon-γ (IFN-γ) and interleukin-6 (IL-6), have been reported in influenza-infected patients who later developed febrile seizures, when compared with the virally infected control subjects without seizures." (PMID 24265605, 2013). "The primary consistent finding in these studies was a positive correlation between IL-6 levels and influenza severity." (PMID 24324838, 2013). "For example, some studies show that IL-6 is released in response to influenza infection and that levels of IL-6 in the upper respiratory tract and in blood correlate with symptoms." (PMID 23441208, 2013). "On day 3 PI, there was an increase in IFN-γ (p = 0.049) and IL-6 (p = 0.03) in BALF from influenza-infected mice." (PMID 23968752, 2013).